REN (renin)
Diseases named in the same sentence as REN in open-access papers (continued):
Sharing a sentence is not in itself a finding about the gene and the disease.
Hypertension (continued). "Causes of renin-mediated hypertension include conditions that decrease renal blood flow including renal artery stenosis after trauma or infection, mass effect from any renal tumor onto the vascular flow, renal artery thrombosis, and very rare renin-secreting tumors such as JGCT." (PMID 40546339, 2025). "For example, the rs61746559 missense variant affecting SGLT4 was previously reported to be additively associated with renin levels, and together with our novel finding that the homozygous genotype is protective for hypertension, it may provide a basis for considering the gene as a drug target." (PMID 40306283, 2025). "In the pathogenesis and progression of hypertension, bile acid metabolism dysregulation is closely associated with endothelial dysfunction, oxidative stress, inflammation, and abnormal activation of the renin–angiotensin–aldosteronerenin-angiotensin-aldosterone system (RAAS)." (PMID 41614751, 2025). "Additionally, high uric acid levels can lead to hypertension because they trigger the renin-angiotensin system and cause problems with blood vessel function, while lower HDL cholesterol decreases the protection of blood vessels due to its anti-inflammatory effects." (PMID 40688902, 2025). "Abnormal preoperative renin concentrations were independently associated with the occurrence of HT at follow-up, suggesting that vascular dysfunction could play a role in hypertension development after successful CoA repair, negatively influencing the long-term prognostic of these patients." (PMID 40283210, 2025). "Following the endorsement of renin inhibitors and the current clinical trials of baxdrostat for managing hypertension, it is crucial to examine how these innovative treatments may influence the inflammatory pathways associated with high blood pressure." (PMID 40109339, 2025). "The activation of the renin–angiotensin–aldosterone system and the sympathetic nervous system, inflammation, oxidative stress and the release of extracellular vesicles (EVs) are some of the underlying mechanisms in the development of hypertension in people with DM type 2 and insulin resistance." (PMID 39201096, 2024). "Additionally, resveratrol’s protective effects against hypertension and kidney damage were associated with increased acetic acid levels, reduced renal expression of Olfr78, and decreased expression of various components of the renin-angiotensin system (RAS)." (PMID 39765786, 2024). "Ang-II signaling, as a final product of the renin–angiotensin system, is known to play a central role in regulating cardiometabolic physiology, and impairments in Ang-II signaling within the CNS have been directly implicated in the development of pathophysiological disorders, such as hypertension." (PMID 39456189, 2024). "Participants with severe hypertension, a secondary cause of hypertension, pregnant, breastfeeding, with moderate-severe cardiovascular and chronic kidney disease, or on medications that confound interpretation of the plasma direct renin or aldosterone concentrations will be excluded." (PMID 39026100, 2024). "Research has increasingly linked low vitamin D levels with hypertension, proposing several mechanisms through which vitamin D might influence blood pressure, including its effects on the renin–angiotensin–aldosterone system (RAAS), inflammation, and endothelial function." (PMID 39796548, 2024). "Some authors proposed that other traditional risk factors (i.e., hypercholesterolemia, hypertension, and obesity) and chronic activation of sympathetic nerves and the renin-angiotensin-aldosterone system may lead to sodium and fluid retention and myocardial fibrosis." (PMID 38926680, 2024). "The study of the functional relationship between insulin and renin-angiotensin signaling systems, which play a key role in the control metabolism and homeostasis, seems particularly important due to the confirmed clinical association between IR and hypertension." (PMID 38323106, 2024).
Hypertension (continued). "Additionally, PM2.5 may cause renin-angiotensin-aldosterone pathway dysfunction, leading to structural and functional kidney changes and resulting in higher BP and elevated hypertension risks." (PMID 39234085, 2024). "Moreover, the beneficial action of AC against CKD-related hypertension might also be linked to the inhibition of the renin-angiotensin system." (PMID 37960279, 2023). "While the sodium dysregulation, increased sympathetic nervous system, and alterations in the renin-angiotensin aldosterone system caused by CKD have primarily been associated with hypertension, these pathologic conditions could lead to the occurrence of other chronic diseases." (PMID 37250643, 2023). "Furthermore, abnormal activation of renin- angiotensin-aldosterone system (RAAS) that specifically occurs with hypertension may further predispose hypertensive adults to the development of NAFLD2." (PMID 37608217, 2023). "Other important factors include the presence of hypertension which, together with the uremic environment, may stimulate multiple pathogenic mechanisms such as activation of the renin-angiotensin-aldosterone system, sympathetic hyperactivity and sodium retention." (PMID 36835051, 2023). "Other underlying mechanisms, such as renin-angiotensin, the sympathetic nervous system, the immunological system, lifestyle, and environmental factors could potentially explain sex differences in the presence of hypertension and cardiovascular diseases." (PMID 37051131, 2023). "ACE2 is an important regulator of renin–angiotensin system that regulates blood pressure, fluid, and electrolyte balance, etc, and its polymorphism in humans has been discovered about 20 years ago and has been linked to cardiovascular diseases, hypertension, and diabetic mellitus, etc." (PMID 36689489, 2023). "It is true that the aldosterone to renin ratio often normalizes, but possible vascular damage and cardiovascular risk is a consequence of both the direct effect of aldosterone at the level of vascular wall and, in a lesser extent, of any other cause of hypertension." (PMID 34847293, 2022). "Although the specific mechanism of lenvatinib-induced hypertension is not fully understood, the possible mechanism is supposed to be associated with the interaction of neurostimulators factors, endothelin signaling pathway, renin–angiotensin aldosterone system and nitric oxide signaling pathway." (PMID 36428618, 2022). "Increased renin mRNA expression in the clipped kidneys was associated with a significant increase in the circulating Ang II level in response to the development of 2K1C hypertension in WT mice at the end of experiment (Control: 35.8 ± 6.5 fmol/mL vs. 2K1C: 115.4 ± 17.8 fmol/mL, p < 0.01)." (PMID 36555438, 2022). "Furthermore, it suggests that different genetic predispositions may affect the occurrence of hypertension, depending on the blood renin concentration." (PMID 35448080, 2022). "Lastly, immune cells that lack VDR have been reported to directly impact on the secretion of miR-106b-5p, which, in turn, may increase renin production by acting on juxtaglomerular cells, thus suggesting the role of inflammation as the cause of renin-driven hypertension." (PMID 34684604, 2021). "In addition, intrauterine growth restriction may lead to impaired function of the hypothalamic-pituitary-adrenal axis and increased activity of renin angiotensin aldosterone system, thereby elevating the risk for hypertension." (PMID 34222359, 2021). "Also, standard anti-hypertensive medication interfering with the renin-angiotensin-aldosterone system may have obscured the association in participants with hypertension." (PMID 32764816, 2020). "We know that hypertension prevalence increases with age and that hypertension prevalence is higher in men than women approximately until the latter approach menopause, with associated mechanisms including the role of the kidneys, the renin–angiotensin system, relaxin, and developmental programming." (PMID 32311000, 2020).
Hypertension (continued). "Moreover, with age, there is a decrease of baroreceptor sensitivity, an increase of responsiveness to sympathetic nervous system stimuli, an alteration of renal and sodium metabolism, and a modification of renin-aldosterone relationship, thereby predisposing to high blood pressure." (PMID 32626776, 2020). "Both high and low circulating levels of renin may be associated with hypertension." (PMID 31581667, 2019). "The efficacy of TZD to reduce arterial pressure depending upon magnitude of renin–angiotensin II pathway activation may, by analogy, suggest that hypertension associated with high sympathetic nervous system activity is insensitive to arterial pressure reduction." (PMID 31543812, 2019). "A previous cohort study showed a spectrum of PA; specifically, more renin suppression with higher aldosterone concentrations was associated with lower serum potassium, higher urinary excretion of potassium and independently associated with an increased risk for incident hypertension." (PMID 31498018, 2019). "Obesity is a risk factor for the development of hypertension, which can increase hypertension through multiple mechanisms, including insulin resistance, activation of sympathetic nervous system, sodium retention leading to increased renal reabsorption and activation of the renin–angiotensin system." (PMID 30828463, 2019). "Additionally, this study measured the important biomarkers such as renin and aldosterone, which are previously known parameters that could associate with increased risk of hypertension and CVD." (PMID 29854085, 2018). "Among other risk factors such as overweight and reduced physical activity, a reduced urine sodium concentrating ability, increased sodium sensitivity, low plasma renin values, mutations of epithelial sodium channels and other genetic factors might contribute to hypertension in Africans." (PMID 30586432, 2018). "The profile of labetalol, an alpha/beta adrenergic antagonist use to treat essential hypertension, shows that its dose reduction is strongly and positively associated with prerenal renal failure and acute renal failure diagnostics as well as lab tests for renin activity and aldosterone." (PMID 30349060, 2018). "Activation of the renin-angiotensin system, inflammation, insulin resistance, decrease in baroceptor sensitivity, endothelial dysfunction, oxidative stress, and hyperleptinemia may also be implicated in the development of hypertension." (PMID 28943894, 2017). "Among the pathophysiological mechanisms, still largely unknown, underlying the association between hypovitaminosis D and hypertension, a key role could be played by vitamin D-mediated suppression of renin biosynthesis through regulation of the renin-angiotensin system (RAS)." (PMID 26000281, 2015). "Genetic and experimental models, such as mice which express human renin and angiotensinogen, renovascular hypertension (e.g., 2-kidney, 1-clip) and infusion of exogenous Ang II, are commonly used approaches to model human hypertension associated with increases in Ang II." (PMID 25400581, 2014). "Since our findings also revealed increased activation of RAAS, it is possible to speculate that the more severe hypertension observed in VDD+TDF could be explained by the increased mRNA expression of renin, AGT, ACE, and AT1a associated with augmented levels of aldosterone." (PMID 25048368, 2014). "The renin-angiotensin system is a major endocrine/paracrine system that regulates blood pressure (BP) in our body, genes encoding components of this system have been strong candidates for the investigation of the genetic basis of essential hypertension and major targets for antihypertensive drugs." (PMID 24860821, 2014).
Hypertension (continued). "A higher incidence of hypertension (66–100%) has been associated with intrarenal neuroblastoma as compared to 27% reported in the literature for neuroblastoma, probably because of compression of renal vessels, increased renin release from the kidney, and a high circulating level of catecholamines." (PMID 24416605, 2013). "Our findings suggest that hypertension plays a role in the early stage of colorectal carcinogenesis by inducing oxidative stress and chronic inflammation, which might be associated with activation of the renin-angiotensin system." (PMID 23860206, 2013). "The exact mechanism by which vitamin D deficiency results in hypertension is unknown but there are several postulated mechanisms including upregulation of the renin-angiotensin system, decreased production of nitric oxide by endothelial cells, and an increase in plasminogen activator inhibitor-1." (PMID 22784560, 2012). "The renin-angiotensin-aldosterone system is involved in alterations of vascular function in hypertensive patients, the study of aldosterone effects on vascular function could be especially relevant in the hemodynamic abnormalities associated with hypertension." (PMID 21492462, 2011). "According to a hypothesis, accesory renal arteries usually have a longer length and a smaller diameter compared to the main artery, and the renal segment supported by this artery display lower blood pressure which cause hypertension by stimulating renin secretion." (PMID 20076808, 2010). "In our opinion, hypertension may also be caused byany of three factors: mechanical compression of the splanchnic vascular bed; asympathetic reflex from the splanchnic regions; and the release of humoralvasoconstriction mediators, such as renin or vasopressin." (PMID 21197458, 2008). "Originating from the juxtaglomerular apparatus, it leads to autonomous renin production and secondary hyperaldosteronism, typically resulting in severe hypertension and hypokalemia." (PMID 41357681, 2026). "Mild obstructive sleep apnea (OSA) is often underdiagnosed but contributes to treatment-resistant hypertension through oxygen deprivation and activation of the renin-angiotensin-aldosterone system." (PMID 42152359, 2026). "Suppression of the renin-angiotensin system specifically and selectively only in adipose tissue alleviates hypertension and atherosclerosis, whereas overexpression of the mineralocorticoid receptor specifically and only in adipocytes promotes vascular injury." (PMID 41668130, 2026). "Simulations of hypertension, induced by various stimuli like increased renin or aldosterone secretion, demonstrated significant effects on parathyroid hormone (PTH), calcitriol, renal Ca2+/Mg2+ handling, and bone resorption." (PMID 41637481, 2026). "This overview explores the intricate pathophysiologic mechanisms driving hypertension in renal insufficiency, including volume overload, renin-angiotensin-aldosterone system (RAAS) activation, sympathetic overactivity, and vascular dysfunction." (PMID 41682931, 2026). "PA is a clinical syndrome characterized by hyperaldosteronism, low renin activity, hypertension, and hypokalemia due to excessive aldosterone synthesis in adrenal cortex." (PMID 40815389, 2026). "The contributions of cardiac structural remodeling, metabolic factors, and the renin-angiotensin-aldosterone system (RAAS) to hypertension in this population remain incompletely understood." (PMID 41646691, 2026). "AME should be considered in children with low-renin, low-aldosterone hypertension, particularly in consanguineous populations." (PMID 42064719, 2026). "Key findings of morphological kidney maldevelopment, altered renin–angiotensin signaling, and hypertension in early-life ID underscore the urgent need for future mechanistic data in animals such as rats." (PMID 40220077, 2026).
Hypertension (continued). "Juxtaglomerular cell tumor (JGCT), or reninoma, is a rare renin-secreting renal neoplasm that typically presents with severe hypertension, hypokalemia, and elevated renin and aldosterone levels." (PMID 41357681, 2026). "JGCTs are uncommon renin-secreting tumors of the kidney, usually seen in young women presenting with difficult-to-control hypertension and hypokalemia." (PMID 41357681, 2026). "Differences were also found between the 4 groups regarding lipid profile, HbA1c levels, body mass index, aldosterone, renin, hypertension treatment, and smoking status." (PMID 41111403, 2026). "Maculae densa are juxtaglomerular cells that control renin secretion, alter renin feedback mechanisms, and contribute to hypertension." (PMID 40220077, 2026). "Emerging evidence suggests that patients with low-renin hypertension (LRH) benefit from targeted treatment with mineralocorticoid receptor antagonists (MRA)." (PMID 42120732, 2026). "Food protein-derived peptides and hydrolysates help lower blood pressure (hypertension) primarily by inhibiting the renin-angiotensin system (RAS)." (PMID 41829173, 2026). "Comorbidities included type 2 diabetes mellitus (n = 6), overweight (n = 10), cancer (n = 1), and hypertension (n = 16), with four patients being on renin‐angiotensin system (RAS) blockade therapy." (PMID 41273049, 2026). "Blood levels of renin and electrolytes, including sodium, potassium, chloride, and calcium, were used to test their relationship with hypertension and blood pressure." (PMID 41598580, 2026). "The typical functional form is the most common and is characterized by elevated plasma renin activity, hyperaldosteronism, hypokalemia, and marked hypertension." (PMID 41357681, 2026). "Hypertension caused by TA-TMA occurs due to primary and direct renal endothelial injury and microthrombosis, which activates the renin–angiotensin–aldosterone system." (PMID 40406401, 2025). "Hypertension arises due to volume expansion, mineralocorticoid excess, sodium retention, vascular remodeling, and suppressed renin–angiotensin system (RAS) activity." (PMID 40507134, 2025). "Pre-eclampsia is associated with dysregulation of the renin–angiotensin–aldosterone system (RAAS), contributing to hypertension and endothelial dysfunction, as previously discussed." (PMID 39941563, 2025). "Summary of randomized controlled trials and real-world evidence comparing renin inhibitors with ACEi and ARBs in hypertension." (PMID 41409925, 2025). "Patients with Wilms' tumors are often asymptomatic; approximately 10 % are discovered incidentally after trauma, whereas 25 % present with microscopic hematuria or hypertension secondary to renin production." (PMID 40674961, 2025). "Enalapril, an angiotensin-converting enzyme inhibitor (ACEI), is commonly prescribed for hypertension and lowers blood pressure via the renin-angiotensin system (RAS)." (PMID 41408352, 2025). "The first included age, duration of arterial hypertension, weight, BMI, DBP, microalbuminuria, eGFR, serum creatinine, and aldosterone-to-renin ratio, all strongly associated with AIx and wave reflection parameters." (PMID 41053441, 2025). "PATIENTS AND METHODS: Clinical and endocrine data in clinostatic position (CP) and orthostatic position (OP) during PST were evaluated in 190 hypertensive patients: 80 with PA and 110 with low-renin HTN." (PMID 41251951, 2025). "In the context of malignant hypertension, the concomitant activation of the renin-angiotensin system and hypertension-induced shear stress in small blood vessels lead to elevated oxidative stress and pro-inflammatory responses." (PMID 40861385, 2025). "The elevated expression and dysregulated distribution of CYP11B2 lead to renin-independent hyperaldosteronism, resulting in the spontaneous hypertension in MU." (PMID 39946402, 2025).